NNMT (nicotinamide N-methyltransferase)
Diseases named in the same sentence as NNMT in open-access papers (continued):
Sharing a sentence is not in itself a finding about the gene and the disease.
pancreatic cancer (16 papers, 2013 to 2024). "NNMT expression is upregulated in pancreatic cancer, where levels of the NNMT enzyme correlate with an increased risk of death." (PMID 32992891, 2020). "For instance, the enzyme nicotinamide N-methyltransferase (NNMT) is overexpressed in pancreatic cancer, contributing to aggressiveness." (PMID 37888452, 2023). "Compared with the normal tissues, in Oncomine database, the results revealed higher expression of NNMT in brain and central nervous system (CNS), breast, cervix, colon, esophagus, stomach, head and neck, kidney, lymphatic system, ovary, and pancreas cancers." (PMID 36817086, 2023). "The expression of NNMT in tissue specimens of 28 chronic pancreatitis patients and 178 pancreatic cancer patients were assayed with immunohistochemistry on tissue microarray." (PMID 26942567, 2016). "To date, there are only very few reports suggesting the possible roles of NNMT in pancreatic cancer and the results are controversial." (PMID 26942567, 2016). "In conclusion, NNMT is upregulated in pancreatic cancer, correlates with unfavorable clinicopathological features and holds the potential to be developed as aprognosticator of patients' survival." (PMID 26942567, 2016). "Yu T, et, al., on the contrary, reported that NNMT silencing and overexpression reduced and enhanced the malignancy of pancreatic cancer cells respectively, suggesting an oncogenic role." (PMID 26942567, 2016). "As for NNMT expression in pancreatic cancer, previous studies have shown that NNMT is upregulated in pancreatic cancer tissue and cell lines as well as in the pancreatic juice obtained from pancreatic cancer patients." (PMID 26942567, 2016). "The elevation of Nicotinamide N-methyltransferase (NNMT) has been reported in pancreatic cancer tissues and cell lines, but its clinical and prognostic implications remain controversial." (PMID 26942567, 2016). "In the light of these observations, coupling the antiangiogenic activity of 8a with NNMT inhibitors may be a promising strategy to improve the outcome of patients with pancreatic cancer, a malignancy that displays little therapeutic options." (PMID 37888452, 2023). "For example, increased NNMT expression in pancreatic cancer creates a “metabolic sink” whereby intracellular SAM levels are reduced due to NNMT overactivity, the consequence of which is the upregulation of the expression of several cancer-related genes such as SNAI2, ADAMTS6, TGFB2, LAMB3 and CNTN1." (PMID 34680055, 2021). "Therefore, the role of NNMT expression level in pancreatic cancer and its clinical significance remain elusive." (PMID 26942567, 2016). "In conclusion, NNMT is upregulated in pancreatic cancer, correlates with unfavorable clinicopathological features and may serve as an independent prognosticator of patients' survival." (PMID 26942567, 2016). "Furthermore, NNMT knockdown in the pancreatic cancer cell line PANC-1 was significantly correlated with reduction of cell proliferation and migration, as well as invasive capacity, suggesting the enzyme involvement in cell proliferation and metastatic potential of tumor cells." (PMID 38504052, 2024). "Moreover, we for the first time revealed that NNMTh tends to correlate with unfavorable clinicopathological features in pancreatic cancer patients and that NNMTh is an independent unfavorable prognosticator of OS, suggesting an oncogenic role of NNMT in this cancer." (PMID 26942567, 2016). "Our recent metabolomics study have revealed nicotinamide N-methyltransferase (NNMT), an enzyme participating in nicotinate and nicotinamide metabolism, as a biomarker for miR-1291-altered pancreatic cancer cell metabolome." (PMID 27322206, 2016).
type 2 diabetes (16 papers, 2015 to 2025). "Our previous study also found a significant association between one SNP variant (rs1941404) in the NNMT gene sequence and type 2 diabetes (T2D) in the Chinese Han population." (PMID 38921477, 2024). "A single‐nucleotide polymorphism in the NNMT gene is associated with Type 2 diabetes." (PMID 40289598, 2025). "Elevated plasma levels of methylated nicotinamide and increased NNMT expression in white adipose tissue have been observed in individuals with Type 2 diabetes, with plasma methylated nicotinamide correlating positively with fasting glucose." (PMID 40289598, 2025). "In human adipose tissue, NNMT expression correlates positively with insulin resistance and type 2 diabetes mellitus." (PMID 41008588, 2025). "Clinically, NNMT expression is significantly upregulated in adipose tissue of patients with type 2 diabetes mellitus and insulin resistance, supporting NNMT inhibition as a potential therapeutic strategy for metabolic risk factors associated with CVD." (PMID 41008588, 2025). "This study demonstrates for the first time that NNMT mRNA in adipose tissue and circulating levels of the product of NNMT, MNA, were higher in humans with insulin resistance or type 2 diabetes and correlated with the extent of insulin resistance." (PMID 25596852, 2015). "We have explored the hypothesis that white adipose tissue (WAT) NNMT expression and plasma 1-methylnicotinamide (MNA) concentration are increased in human insulin resistance and type 2 diabetes." (PMID 25596852, 2015). "Importantly, higher urinary concentrations of the NNMT product MNA and its oxidation product N-methyl-2-pyridone-5-carboxamide were observed in mouse and rat models of type 2 diabetes and in humans with type 2 diabetes." (PMID 25596852, 2015).
glioma (15 papers, 2018 to 2025). A benign or malignant brain and spinal cord tumor that arises from glial cells (astrocytes, oligodendrocytes, ependymal cells). "The present study aimed to investigate the role of NNMT in glioma and to elucidate the associated functional mechanisms." (PMID 35884600, 2022). "In U251 glioma cells, knockdown of NNMT resulted in an increase in the NAD/NADH ratio in a low-glucose environment." (PMID 35884600, 2022). "The gene expression profiles of U87 and U251 glioma cells after NNMT knockdown were analyzed and experimentally validated using qRT-PCR and Western blot." (PMID 35884600, 2022). "Scratch test results of U87 and U251 glioma cells revealed that cell migration was inhibited after NNMT knockdown." (PMID 35884600, 2022). "NNMT knockdown reduced the volume of glioma and improved the prognosis and survival time of patients with glioma." (PMID 35884600, 2022). "Knockdown of NNMT reduced the invasive ability of glioma cells, and downregulation of its downstream protein GAP43 occurred due to altered cellular methylation caused by NNMT overexpression." (PMID 35884600, 2022). "The glioma xenograft mouse models were used to verify the regulatory role of NNMT, GAP43, and SIRT1." (PMID 35884600, 2022). "In this investigation, the TCGA database was used to examine the differential expression of NNMT in 33 tumor tissues, and it was found that NNMT appeared to be highly expressed in glioma." (PMID 35884600, 2022). "High DEGs in grade II gliomas included NNMT, MFAP5, APCDD1L-AS1, C7orf57, HP, SERPINA5, and LTF and some highly downregulated DEGs included ABCA4, PDE6A, GRP, RD3, and TMEM72." (PMID 33948562, 2021). "Particularly, it was shown that nicotinamide N-methyltransferase (NNMT) is preferentially expressed in glioma stem cells; NNMT depletes 5-adenosyl-methionine (SAM), a methyl donor generated from methionine." (PMID 30279357, 2018). "Elevations in NNMT activity have been documented across various malignancies, including bladder, breast, colorectal, gastric, lung, oral cavity, ovarian, and prostate cancers, as well as in gliomas, lymphomas, and insulinomas." (PMID 38921477, 2024). "Previous studies have demonstrated the function of ABCC3, HOXA4, HOXC10, and NNMT in gliomas." (PMID 37334354, 2023). "Moreover, we observed that upregulation of NNMT expression promoted glioma proliferation and disease progression in patients." (PMID 35884600, 2022). "NNMT knockdown reduced the volume of mice xenograft glioma and the viability of glioma cells." (PMID 35884600, 2022). "Notably, the protein expression of NNMT increased in patients with different grades of glioma, as determined by immunohistochemical and Western blot analyses." (PMID 35884600, 2022). "Additionally, NNMT was knocked down in two types of glioma cells, U87 and U251, to evaluate the invasive ability of these cells." (PMID 35884600, 2022). "Other fc3 genes in the curated set, FERMT1, TMEM100, DYNLT3, EPHB1, IGFBP2, NNMT, and SH3GL2 all show direct evidence to a relationship with glioma biology and patient prognosis." (PMID 39941811, 2025). "In comparison to other glioma subtypes, the GS2 exhibited higher expression levels of IBSP, PLA2G2A, NNMT, CA9, and MMP9, while the GS5 showed higher expression levels of CHI3L1, IGFBP2, EMILIN3, MEOX2, and PDPN." (PMID 38332637, 2024). "Other mitochondrial genes such as ABCC3, HOXA4, HOXC10, NNMT, and SCNN1B are typically increased in their expression as the grade of glioma and the higher expression of these genes have been associated with poor prognosis in LGG." (PMID 39012280, 2024). "In the present study, we found that nicotinamide N-methyltransferase (NNMT) is a key factor influencing the occurrence and development of glioma." (PMID 35884600, 2022). "In contrast, NNMT silencing could activate tumor suppressor PP2A and inactivate oncogenic STKs, thereby inhibiting glioma-forming ability and enhancing radiation sensitivity." (PMID 37334354, 2023).
glioma (continued). "Moreover, the regulatory roles of NNMT, GAP43, and SIRT1 were confirmed in glioma xenograft mouse models." (PMID 35884600, 2022).
Insulin resistance (15 papers, 2015 to 2025). Increased resistance towards insulin, that is, diminished effectiveness of insulin in reducing blood glucose levels. "In agreement with the previous study, our results showed upregulated NNMT, which correlates positively with insulin resistance, and downregulated GNMT, deficiency of which is known to impair glucose tolerance and insulin sensitivity." (PMID 32518576, 2020). "Here we explore the hypothesis that elevated nicotinamide-N-methyltransferase (NNMT) expression and activity may play a role in the development of human insulin resistance." (PMID 25596852, 2015). "The expression of nicotinamide N-methyltransferase (NNMT) is increased in the white adipose tissue (WAT) and liver tissue of patients with insulin resistance or T2DM." (PMID 37244925, 2023). "Thus, NNMT inhibition may provide a novel therapeutic approach for insulin resistance." (PMID 25596852, 2015).
diabetes (14 papers, 2015 to 2025). "In our previous studies, significant associations were observed between NNMT gene polymorphisms and various age-related diseases, including diabetes and cardiovascular diseases." (PMID 38921477, 2024). "Research on NNMT is currently focused on inhibitors, as therapeutic agents of many NNMT-related pathways, such as cancer or diabetes." (PMID 36361996, 2022). "It is apparent that NNMT is significantly expressed in metabolically active tissues like livers and adipose tissues, as well as in conditions involving heightened metabolic requirements, such as aging and age-related diseases, including cancer and diabetes." (PMID 38921477, 2024). "Collectively, this panoramic view articulates a core mitochondrial dysfunction signature common to sarcopenia and diabetes, a classical adipokine–mitochondria support network, a novel counter-regulatory myokine/adipokine module, and tissue- and disease-specific modifiers (NNMT, LEP, and AdipoQ)." (PMID 40869253, 2025). "Although the underlying mechanisms for this observation are not clear, we postulate that individuals without diabetes may be able to mitigate the influence of high WAT NNMT expression on plasma MNA levels by a mechanism that is compromised in patients with diabetes." (PMID 25596852, 2015). "Authors have recently intensified their focus on NNMT’s function as a critical modulator of NAD+ and Hcy metabolic pathways, particularly in the context of age-related pathologies such as neurodegenerative disorders, diabetes, cardiovascular conditions, and cancers." (PMID 38921477, 2024). "A lead molecule, JBSNF-000028, was identified that inhibits human and mouse NNMT activity, reduces MNA levels in mouse plasma, liver and adipose tissue, and drives insulin sensitization, glucose modulation and body weight reduction in a diet-induced obese mouse model of diabetes." (PMID 36104373, 2022).
bladder cancer (13 papers, 2009 to 2024). "Recently, NNMT expression has been associated with a mesenchymal signature in bladder cancer and renal cancer." (PMID 33446144, 2021). "The importance of NNMT in cell proliferation and migration has recently been underlined in human bladder cancer cells, where NNMT expression was suggested to be necessary for cell growth and migration." (PMID 23990942, 2013). "In addition, NNMT overexpression was found to be associated with increased tumorigenesis of colorectal cancer, bladder cancer, squamous cell carcinoma, and clear cell renal cell carcinoma." (PMID 33193702, 2020). "Moreover, NNMT has been associated with radiation resistance in bladder cancer cells and cancer stem cells." (PMID 27323852, 2016). "The lack of PARP inhibition exerted by nicotinamide, which is depleted by NNMT activity, could be the main cause for the elevated radiation resistance of a bladder cancer cell line, and a tumorigenic mesenchymal cancer stem cell clone, in which NNMT was found to be overexpressed." (PMID 23990942, 2013). "In human bladder cancer cell lines, the enzyme silencing led to a significant decrease in cell migration, highlighting the crucial role of the NNMT in tumor metastasis and invasion." (PMID 38504052, 2024). "To determine the relevance of these observations to human tumors, we measured the expression of AURKA and NNMT in 423 primary bladder cancers using immunohistochemistry and image analysis on tissue microarrays." (PMID 28102366, 2017). "In in vitro studies, up-regulation of AURKA inhibited NNMT expression, which in turn contributed to bladder cancer invasion." (PMID 28102366, 2017). "Our observation that NNMT inhibits invasion and metastasis in bladder cancer cells was completely unexpected." (PMID 28102366, 2017). "Together, our results demonstrated that AURKA and NNMT play antagonistic roles in the regulation of invasion in bladder cancer cells in vitro." (PMID 28102366, 2017). "Our data are consistent with the results derived from bladder cancer cells, KB cancer cells, oral carcinoma cells and renal cancer cells, which strongly suggested that NNMT plays an important role in cancer cell growth in vitro and in vivo." (PMID 24558488, 2014). "On the other hand, a recent in vitro study found that NNMT was necessary for cancer cell migration in bladder cancer cell lines, pointing to a possible involvement in tumor invasion." (PMID 19216803, 2009). "Overexpression of NNMT has been implicated in various cancers, including but not limited to colon, lung, hepatocellular, and bladder cancer." (PMID 33446144, 2021). "In addition, we reported an overexpression of tissue and urinary NNMT in bladder cancer, indicating that NNMT could represent a potential biomarker for early and non-invasive diagnosis of these malignancies." (PMID 23990942, 2013). "In our previous reports, we analysed NNMT expression in renal cell carcinoma, OSCC, bladder cancer and non-small cell lung cancer." (PMID 23990942, 2013). "We should emphasize that although there is enrichment of the AURKA signature comprising its downstream target genes in basal bladder cancer not all AURKA overexpressing tumors show downregulation of NNMT." (PMID 28102366, 2017). "Interestingly, we recently demonstrated that NNMT expression levels were significantly higher in saliva and urine samples of patients with OSCC and bladder cancer, respectively, compared to controls." (PMID 23990942, 2013). "The most potent NNMT inhibitor identified so far, 17u, has an IC50 value of 3.7 nM, but the inhibition of tumor growth only appeared when tested at 100 μM concentration in oral, lung, and bladder cancer cell lines, and this difference may be related to the poor cellular permeability of compound 17u." (PMID 35884600, 2022).
hepatocellular carcinoma (13 papers, 2009 to 2025). A malignant tumor that arises from hepatocytes. "Nicotinamide N-methyltransferase (NNMT) modulates the metabolism of hepatoma cells and can be induced by activated HSCs." (PMID 37007125, 2023). "Accordingly, in hepatocellular carcinoma, NNMT downregulates H3K27 methylation and transcriptionally activates a cluster of differentiation 44 (CD44), a stem cell marker." (PMID 34073600, 2021). "CD44 has also been reported to be a direct target of nicotinamide N-methyltransferase (NNMT) in hepatocellular carcinoma." (PMID 33303029, 2020). "We report here that activated HSCs induce upregulation of nicotinamide N‐methyltransferase (NNMT), which is known to regulate multiple metabolic pathways in hepatoma cells of the liver." (PMID 31294922, 2019). "TGF‐beta can indeed upregulate the expression of NNMT in hepatoma cells, and the mechanism will continue to be further studied." (PMID 31294922, 2019). "In this study, human hepatoma cell lines showed a significant upregulation in NNMT mRNA levels when treated with HSC‐derived conditioned media (CM)." (PMID 31294922, 2019). "In the present study, we found that activated HSCs upregulated NNMT expression levels in hepatoma cells, based on our previous study and other reports, which is most likely the result of TGF‐β secretion by the HSCs." (PMID 31294922, 2019). "In addition, phalloidin staining of the cytoskeleton showed a gradual decline in microfilament density with increasing drug dose, indicating that statins not only inhibit NNMT expression but also the motility of hepatoma cells." (PMID 31294922, 2019). "NNMT was also a target of statins, which inhibited metastasis of hepatoma cells." (PMID 31294922, 2019). "Therefore, we explored the effect of common cholesterol‐lowering drugs on NNMT expression and found that NNMT was a target of statins that inhibited metastasis of hepatoma cells in vitro and in vivo." (PMID 31294922, 2019). "Finally, NNMT was also shown to be a target of statins that inhibited metastasis of hepatoma cells." (PMID 31294922, 2019). "Consequently, the elevation of Hcy levels due to the NNMT-catalyzed methylation of NAM may constitute a pivotal mechanism through which NNMT influences the onset and advancement of hepatocellular carcinoma, highlighting that defects in Hcy metabolism could contribute to cancer development." (PMID 40427612, 2025). "Finally, NNMT and GNMT did not affect each other’s expression levels in SMMC‐7721 cells, and their mRNA levels were not correlated in hepatoma cell lines." (PMID 31294922, 2019).